RN7SL836P (RNA, 7SL, cytoplasmic 836, pseudogene)
Gene: Miscellaneous RNA gene on chromosome 19 (45,651,510 to 45,651,805, forward strand). Ensembl gene ENSG00000241226.
Homologues: Orthologues: chimpanzee Metazoa_SRP (97% identical), macaque Metazoa_SRP (91% identical). Paralogues in human: RN7SL2 (84% identical), RN7SL1 (84% identical), RN7SL3 (83% identical), RN7SL769P (82% identical), RN7SL45P (82% identical), RN7SL444P (81% identical), RN7SL7P (81% identical), RN7SL448P (80% identical), RN7SL709P (80% identical), RN7SL43P (80% identical), RN7SL493P (80% identical), RN7SL625P (80% identical), and 704 more.